FRMD6-AS2 (FRMD6 antisense RNA 2)
Synonyms: C14orf82; FRMD6-AS1
Gene: Long non-coding RNA gene on chromosome 14 (51,379,509 to 51,651,744, reverse strand). Ensembl gene ENSG00000258537.
Diseases named in the same sentence as FRMD6-AS2 in open-access papers:
FRMD6-AS2 is named in the same sentence as 1 disease in open-access papers, as found by Europe PMC text mining. Sharing a sentence is not in itself a finding about the gene and the disease. The quoted sentences say what the papers report.
endometrial cancer (1 paper, 2025). Primary or metastatic malignant neoplasm involving the endometrium (mucous membrane that lines the endometrial cavity). "FRMD6 antisense RNA 2 (FRMD6-AS2) is a noncoding RNA, and it has been shown that it may have anticancer effects on endometrial cancer." (PMID 40104507, 2025).